FGF2 (fibroblast growth factor 2)
Diseases named in the same sentence as FGF2 in open-access papers (continued):
Sharing a sentence is not in itself a finding about the gene and the disease.
chondrosarcoma (14 papers, 2008 to 2025). A malignant cartilaginous matrix-producing mesenchymal neoplasm arising from the bone and soft tissue. "We found that meclozine, an anti-histamine drug that has long been used for motion sickness, facilitates chondrocyte proliferation and mitigates loss of extracellular matrix in FGF2-treated rat chondrosarcoma (RCS) cells." (PMID 24324705, 2013). "FGF2 treatment caused an elevation in the expression of p21, leading to the formation of complexes involving cyclin D2-Cdk4-p21, cyclin D2-Cdk2-p21, and cyclin E-Cdk2-p21, and reducing the activity of cyclin-dependent kinase 2 (Cdk2) and cyclin E-dependent kinases in rat chondrosarcoma cells." (PMID 40256430, 2025). "VEGF and FGF2, which have an intense crosstalk, are the two main growth factors involved in chondrosarcoma angiogenesis." (PMID 29361725, 2018). "Administration of FGF2 can induce the up-regulation of P21WAF1 and p27Kip1, cell cycle inhibitors, and inhibit the proliferation in rat chondrosarcoma cells." (PMID 40256430, 2025). "In summary, vascularization is an important step during chondrosarcoma progression and appears to be predominantly mediated by VEGF and FGF2." (PMID 29361725, 2018). "What's more, in rat chondrosarcoma (RCS) chondrocyte model, CNP counteracts fibroblast growth factor 2 (FGF2) effects (which inhibit proliferation and trigger matrix degradation) by inhibiting the Erk pathway at the level of Raf-1." (PMID 28337152, 2017). "Meanwhile, FGF2 has been reported to regulate MMP-13 expression with a time- and dose-dependent relation in chondrosarcoma cells, leading to the degradation of extracellular migration inhibitory factor (MIF) to promote cancer metastasis." (PMID 28740507, 2017). "As rat chondrosarcoma (RCS) chondrocytic cells express high levels of FGFR3, exogenous administration of FGF2 readily recapitulates cellular processes occurring in FGFR3-related skeletal dysplasias." (PMID 24324705, 2013). "VEGF, FGF2, endothelin-1 (ET-1) and hypoxia-inducible factor-1α (HIF-1α) expression and mitogen activated protein kinase (MAPK) signaling are significantly enhanced in G2 and G3 conventional chondrosarcomas compared to G1 chondrosarcomas." (PMID 29361725, 2018). "Rat chondrosarcoma chondrocytes (RCS), however, are not able to respond to Noggin in this fashion unless growth arrest is induced by FGF2." (PMID 28523267, 2017).
cognitive deficits (14 papers, 2020 to 2026). "Previous investigations have alluded to the potential association between Fgf2 and anesthesia-induced cognitive impairment in elderly individuals." (PMID 38493090, 2024). "To investigate the mechanism of the impact of sevoflurane-induced Fgf2 expression on cognitive impairment, we isolated and cultured primary rat cortical neurons and constructed an in vitro cell model (Sevo model neurons) induced by sevoflurane." (PMID 38493090, 2024). "The current research delineates how Fibroblast Growth Factor 2 (Fgf2) modulates tau protein phosphorylation, contributing to cognitive impairments in aged rats upon sevoflurane administration." (PMID 38493090, 2024). "In addition, the present results suggest a strategy for the development of a method to prevent and treat the cognitive impairment associated with delayed CO encephalopathy; antidepressants such as TCAs, SSRIs, and SNRIs may be useful by increasing FGF2 expression in astrocytes." (PMID 33737717, 2021). "However, within the context of sevoflurane-induced cognitive impairment in the elderly, the precise contribution of Fgf2 has remained an enigma." (PMID 38493090, 2024). "Consequently, these findings provide compelling empirical evidence for Fgf2’s involvement in the intricate molecular mechanisms governing cognitive impairment, accentuating its potential as a pivotal target for future therapeutic interventions." (PMID 38493090, 2024). "Moreover, in vivo E2 replacement suppressed FGF2 signaling and rescued the compromised reactive astrogliosis and cognitive deficits." (PMID 32817249, 2020). "In AD, preliminary evidence has shown FGF2 improved cognition by modulating ferroptosis and supporting neuronal survival, whereas YAP1 mitigates cognitive deficits and reverses AD pathology via CDK6 signaling or artemisinin activation." (PMID 40933191, 2025). "FGF2-Akt and BDNF-TrkB signaling pathways were reactivated by Rg1 in the hippocampus and prefrontal cortex to inhibit neuronal apoptosis and prevent cognitive deficits." (PMID 32410834, 2020). "Therapeutic agents directed at mitigating tau aggregation and clearing Aβ1-42, and delivery of growth factor genes (BDNF, FGF2), have ameliorated cognitive deficits, but these approaches did not prevent or stop AD progression." (PMID 37369719, 2023). "FGF2-Akt and BDNF-TrkB signaling pathways were reactivated by Rg1 in the hippocampus and prefrontal cortex to inhibit neuronal apoptosis and prevent cognitive deficits and experimental basis for the development and use of ginsenoside for anti-aging and age-related diseases." (PMID 34964700, 2022).
endometriosis (14 papers, 2012 to 2025). The growth of functional endometrial tissue in anatomic sites outside the uterine body. "Although some studies have involved FGF2 and endometriosis, the source of elevated FGF2 in the lesion, peritoneal fluid, or peripheral blood and its role in the pain associated with endometriosis need to be further explored." (PMID 36845134, 2023). "Taken together, these results suggested that the enhanced secretion of FGF2 in mast cells may be a potential cause of endometriosis-associated pain in women." (PMID 36845134, 2023). "This study’s focus moved on to women with endometriosis to clarify the role of mast-cells-derived FGF2 in endometriosis-related pain." (PMID 36845134, 2023). "Estrogen-stimulated mast cells enhanced the concentration of FGF2 in endometriotic lesions and aggravated endometriosis-related pain in vivo." (PMID 36845134, 2023). "The FGF2 level was higher in patients with ovarian endometriotic cyst and deep infiltrated endometriosis lesions than in patients with peritoneal endometriotic lesions." (PMID 36845134, 2023). "A significant increase in the concentration of FGF2 was observed in the peritoneal fluid of patients with endometriosis in stages III and IV compared with the control patients and those in stages I and II." (PMID 36845134, 2023). "Several studies have reported the elevated FGF2 in lesions, peritoneal fluid, or peripheral blood in patients with endometriosis." (PMID 36845134, 2023). "The increased FGF2 plays a vital role in the mast cell-nerve crosstalk, which contributes to endometriosis-related pain." (PMID 36845134, 2023). "The number of FGF2 positive mast cells were increased in ovarian endometriosis lesions than control endometrium from non-endometriosis patients." (PMID 36845134, 2023). "Out of these nine cytokines, three have already been shown to be increased in the FF (IL1 β, IL6, and IL8), two in the peritoneal fluid (MCP-1 and basic FGF (FGF2)), and one in the serum of women with endometriosis." (PMID 32370059, 2020). "The role and function mechanism of FGF2 in endometriosis-related pain deserves in-depth study." (PMID 36845134, 2023). "The levels of fibroblast growth factor 2 (FGF2) secreted by mast cells and FGFR1 receptors expressed on nerve fibers are significantly elevated in endometriosis patients." (PMID 40004233, 2025). "The results of the present work showed that increased concentration of FGF2 around nerve fibers in endometriosis interact with elevated FGFR1 level on nerve fibers and trigger endometriosis-related pain symptoms." (PMID 36845134, 2023). "Elevations of fibroblast growth factor-2 (FGF-2), angiogenin, and soluble Flt-I (VEGFR-1) in serum of women with endometriosis have all been recorded." (PMID 26240814, 2015). "In addition, introducing the fibroblast growth factor receptor 1 (FGFR1) inhibitor NSC12 could reverse the effect of FGF2 in DRG cells and reduce the pain hyperalgesia of endometriosis rats." (PMID 36845134, 2023). "Moreover, the FGF2 concentration in pelvic fluid was higher in the minimal-pain group and severe-pain group than in patients without endometriosis-related pain." (PMID 36845134, 2023). "The concentration of FGF2 in ascites and the protein level of fibroblast growth factor receptor 1 (FGFR1) were higher in patients with endometriosis than in those without endometriosis, and they were correlated with pain symptoms." (PMID 36845134, 2023).
hemangioma (14 papers, 2012 to 2025). A benign vascular lesion characterized by the formation of capillary-sized or cavernous vascular channels. "A previous report that showed higher serum FGF2 in patients with hemangioma than in healthy control individuals also suggested that FGF2 is a critical growth factor for infantile hemangioma." (PMID 33400686, 2021). "PDGF-BB is one of the growth factors known to be directly involved in the hemangioma onset and to inhibit hemangioma involution along with FGF-2, a known potent regulator of endothelial cells and mast cells, both strongly involved in hemangioma onset." (PMID 24599340, 2014). "Endothelial cell proliferation marks the active growth phase of a hemangioma, during which there is an overexpression of cytokines and angiogenesis-related molecules like fibroblast growth factor 2 (FGF-2), vascular endothelial growth factor A (VEGF-A), and matrix metalloproteinases." (PMID 39040727, 2024). "Many RTK growth factors, such as VEGF, PDGF, FGF2, and EGF, have been demonstrated in the pathogenesis of hemangioma." (PMID 33400686, 2021).
pressure ulcers (14 papers, 2016 to 2025). "Several clinical studies have shown that FGF-2 functions to exert anti-fibrotic effects under conditions as diverse as burns, chronic wounds, oral ulcers, vascular ulcers, diabetic ulcers, pressure ulcers, and surgical incisions." (PMID 36163231, 2022). "In the current study, we sought to improve FGF2 biological activity for its potential use in the regenerative/repair medical settings, such as treatment of burns, chronic wounds, pressure ulcers, diabetic foot, and critical limb ischemia." (PMID 32526859, 2020). "Compared with FGF7 and FGF 10, FGF2 has been used more widely for wound healing, and rh-FGF2 showed potential healing effects for treatment of pressure ulcers, diabetic foot ulcers, and second-degree burns." (PMID 29949887, 2018). "In one randomized controlled trial, patients with pressure ulcers (stage III/IV) which were treated with rh-FGF2 showed better wound closure." (PMID 29949887, 2018). "A major clinical focus in China has been the use of FGF2 as a repair/regeneration factor in conditions as diverse as burns, chronic wounds, oral ulcers, vascular ulcers, diabetic ulcers, pressure ulcers and surgical incisions." (PMID 26793421, 2016). "In a clinical study, FGF-2-treated pressure ulcer patients experienced faster wound closure." (PMID 36613772, 2022). "From the clinical translational point of view, FGF2 has been successfully used as a repair/regeneration factor in a variety of conditions such as burns, chronic wounds, oral ulcers, vascular ulcers, diabetic ulcers, pressure ulcers and surgical incisions." (PMID 28544332, 2017). "It is well known that EGF and FGF2 play major roles in wound healing, and both have been used as regeneration factors in a diverse range of conditions, including burns, chronic wounds, oral ulcers, vascular ulcers, diabetic ulcers, pressure ulcers, and surgical incisions." (PMID 34306094, 2021).
pulmonary hypertension (14 papers, 2012 to 2025). Increased pressure within the pulmonary circulation due to lung or heart disorder. "FGF-2 plays a role in the pathogenic process of pulmonary arterial hypertension, which modifies pulmonary vascular remodelling leading to the vascular manifestations in SSc." (PMID 31178673, 2019). "Because pulmonary hypertension is associated with the overexpression or activation of several RTK receptors, including those for PDGF, FGF2 and EGF, our study aimed to target the majority of these RTK receptors through Suramin treatment." (PMID 24143201, 2013). "In humans, it was shown that APLN indirectly regulates the expression of FGF2 and FGFR1 in pulmonary arterial hypertension via its microRNA mediators miR-424 and miR-503." (PMID 32252341, 2020).
rheumatoid arthritis (14 papers, 2012 to 2026). A chronic, systemic autoimmune disorder characterized by inflammation in the synovial membranes and articular surfaces. "Conversely, in patients with rheumatoid arthritis, increased FGF2 expression induces M1 macrophage polarization and inflammatory factor release, causing joint damage." (PMID 39436561, 2024). "VEGF and FGF-2 are two angiogenic growth factors whose activation leads to dysregulated blood vessel formation as seen in various chronic inflammatory conditions such as cancer and rheumatoid arthritis." (PMID 23132960, 2012).
endothelial dysfunction (13 papers, 2010 to 2025). In vascular diseases, endothelial dysfunction is a systemic pathological state of the endothelium (the inner lining of blood vessels) and can be broadly defined as an imbalance between vasodilating and vasoconstricting substances produced by (or acting on) the endothelium. "These evidences are in accordance with data provided from several labs describing PTX3 as a biomarker of endothelial dysfunctions, regulating nitric oxide, P-selectin, and fibroblast growth factor-2 production." (PMID 32508664, 2020). "Furthermore, BPD is associated with higher concentrations of vascular endothelial growth factors (VEGF) and fibroblast growth factors (FGF-2), both of which contribute to endothelial dysfunction and vasculopathy." (PMID 39596351, 2024). "Endothelial dysfunction is a consequence of increased oxidative stress, reduced NO production, increased secretion of adipokines, endothelin-1, and fibroblast growth factor 2 (FGF-2), which stimulate inflammatory pathways, intimal growth, angiogenesis, and proliferation of smooth muscle cells." (PMID 38474219, 2024). "Clinically, an increase in CO and SV with preserved HR is consistent with isolated systolic hypertension, and the absence of Hi FGF2 could be causing abnormal aortic morphology and endothelial dysfunction." (PMID 24244870, 2013). "Moreover, PTX3 mediates angiogenesis by influencing Fibroblast Growth Factor-2 (FGF-2) activity and is a marker of endothelial dysfunction reflecting vascular inflammatory state in many diseases such as small vessel vasculitis." (PMID 20920344, 2010).
glaucoma (13 papers, 2011 to 2024). Increased pressure in the eyeball due to obstruction of the outflow of aqueous humor. "There was a clear upregulation of inflammatory/immune response genes in the retina detectable at the earliest glaucoma time point, including Gfap, Osmr, Fgf2, Edn2, Stat3, and Socs3." (PMID 37762022, 2023). "Several NTFs have been reported to be associated with glaucoma, including nerve growth factor (NGF), brain-derived neurotrophic factor (BDNF), ciliary neurotrophic factor (CNTF), fibroblast growth factor 2 (bFGF), glial-derived neurotrophic factor (GDNF), and neurturin." (PMID 36579616, 2022). "Neurotrophic factors such as nerve growth factor (NGF), BDNF, CNTF, FGF-2, glial cell-line-derived neurotrophic factor (GDNF), neurturin (NRTN), and neuritin are particularly relevant to glaucoma." (PMID 39458902, 2024). "In a glaucoma model and after ischemia/reperfusion of the retina, MSC increase RGC survival and the expression of CNTF and FGF-2 in the retina." (PMID 25347773, 2014). "Interestingly, we found 8 genes (FN1, THBS1, EPHB2, FGF2, DAB2, CD9, PLAUR and ITGA4) were crucial, suggesting that these genes might function as key factors in the pathogenesis of glaucoma." (PMID 31680442, 2020).
keloid (13 papers, 2007 to 2025). An irregularly shaped, elevated mark on the skin caused by deposits of excessive amounts of collagen during wound healing. "CircPDE7B directly sponged miR-661, which then governed FGF2 gene expression, suggesting a novel circPDE7B/miR-661/FGF2 pathway underlying keloid formation and possible treatment." (PMID 37993257, 2023). "The circPDE7B/miR-661/FGF2 ceRNA regulatory axis plays crucial roles in the pathogenesis of keloids." (PMID 36439262, 2022). "The expression of FoxO1 is highly increased in fibroblasts and inflammatory cells in keloid scars and the gene expression levels of several wound growth factors, including FGF2, Notch1, and ADIPOQ, are also decreased in keloid scars." (PMID 34418600, 2021). "Conversely, transfection with siRNA targeting ATF3 led to decreased cell viability and collagen synthesis via inhibiting TGF-β1 and FGF2/8 production in keloid fibroblasts." (PMID 33315500, 2021). "Conversely, transfection with siRNA targeting ATF3 led to decreased cell viability and collagen synthesis via inhibiting transforming growth factor-β1 (TGF-β1) and fibroblast growth factor 2/8 (FGF2/8) production in keloid fibroblasts." (PMID 33315500, 2021). "Elevated expression of PDGF-C, VEGF and FGF2 in leiomyomas as compared to keloids and adhesions imply an additional role for these angiogenic factors in pathogenesis of leiomyomas." (PMID 17718906, 2007). "At the wound site, the remodelling effect of FGF2 takes place as a result of efficient inhibition of fibroblast terminal differentiation to myofibroblast, which is a key mediator when it is activated in keloids and hypertrophic scars." (PMID 38562669, 2024). "The FGF2 signaling pathway among fibroblasts was significantly inhibited in keloids treated with TAC+5-FU, suggesting that it may be a potential pathway target." (PMID 37275903, 2023). "Additionally, miR-196b-5p inhibitors can promote the viability of keloid fibroblasts and the level of extracellular matrix, which is achieved by targeting FGF2." (PMID 35068324, 2022). "Collectively, hsa_circ_0043688 modulated keloid progression via miR-145-5p/FGF2." (PMID 36439262, 2022). "Confocal microscopy showed strong co-localisation of LTBP-2 and FGF-2 in fibrotic keloid tissue suggesting that the two proteins may interact in vivo." (PMID 26263555, 2015). "In terms of mechanism, the circPTPN12/MiR-21-5p/SMAD7 axis plays a vital role during keloid formation, and a significant increase in circPDE7B has been observed in human keloid tissues and human KFBs, accompanied by miR-661 downregulation and FGF2 upregulation." (PMID 37993257, 2023).
liver cancer (13 papers, 2011 to 2024). An epithelial or non-epithelial malignant neoplasm that arises from the liver. "The MCF2L-AS1-miR-33a-5p-FGF2 axis was likely to be implicated in the pathological processes of liver cancer, and MCF2L-AS1 possibly functioned as a potential biomarker for the early screening and diagnosis of cancer." (PMID 37432067, 2023). "Western blot showed that as opposed to adjacent normal tissues, an increased expression of FGF2 protein was detected in liver cancer tissues." (PMID 37432067, 2023). "The intention of the research is to delve into the influence of MCF2L-AS1, miR-33a-5p and FGF2 on liver cancer cell proliferation, invasion, migration and apoptosis, as well as to examine the regulatory mechanism of the MCF2L-AS1-miR-33a-5p-FGF2 axis in the context of HCC." (PMID 37432067, 2023). "In patients with liver cancer, FGFs (FGF2, FGF4, FGF5, FGF9, and FGF22) are overexpressed." (PMID 31031647, 2019). "To examine the effect of losartan on angiogenic activity in human liver cancer cells, we evaluated VEGF-A, IL-8, and FGF2 production by AT-II stimulation in liver cancer lines." (PMID 33807929, 2021). "In addition, previous studies have shown elevated expression of FGFR ligands, including FGF1 and FGF2, in primary HCC tissues and hepatic cancer cell lines, strongly suggesting FGF signaling plays a key role in the development of HCC." (PMID 21573021, 2011).